UQCC1 (ubiquinol-cytochrome c reductase complex assembly factor 1)
Description:
Required for the assembly of the ubiquinol-cytochrome c reductase complex (mitochondrial respiratory chain complex III or cytochrome b-c1 complex). Involved in cytochrome b translation and/or stability.
Synonyms: bFZb; C20orf44; UQCC; FLJ10850; CBP3
Tractability: Antibody: the Human Protein Atlas places it where antibodies can reach. PROTAC: ubiquitination databases record sites on it; its protein half-life has been measured.
Gene: Protein-coding gene on chromosome 20 (35,302,566 to 35,412,070, reverse strand). Ensembl gene ENSG00000101019.
Subcellular location: Mitochondrion inner membrane; Cytoplasmic vesicle
Subcellular location (Human Protein Atlas): Plasma membrane; Actin filaments; Nucleoplasm
Pathways (Reactome):
Metabolism: Complex III assembly
Gene Ontology:
Molecular function: protein binding
Biological process: mitochondrial respiratory chain complex III assembly
Cellular component: mitochondrial inner membrane; mitochondrion; Cbp3p-Cbp6 complex; cytoplasmic vesicle
Genetic constraint (gnomAD): Loss-of-function variants: 29 observed, 34.67 expected, observed/expected ratio (o/e) 0.84, 90% interval 0.62 to 1.14. The upper end of that interval is the gene's LOEUF score, 1.14, which puts it in group 5 of 6, group 1 being the genes least tolerant of losing a copy. Missense variants: 276 observed, 284.65 expected, observed/expected ratio (o/e) 0.97, 90% interval 0.88 to 1.07. Synonymous variants: 85 observed, 99.74 expected, observed/expected ratio (o/e) 0.85, 90% interval 0.71 to 1.02.
Homologues: Orthologues: chimpanzee UQCC1 (99% identical), macaque UQCC1 (96% identical), pig UQCC1 (92% identical), dog UQCC1 (90% identical), rabbit UQCC1 (90% identical), mouse Uqcc1 (88% identical), guinea pig UQCC1 (87% identical), rat Uqcc1 (86% identical), tropical clawed frog uqcc1 (61% identical), zebrafish uqcc1 (55% identical), Drosophila melanogaster Uqcc1 (28% identical), Caenorhabditis elegans C35D10.5 (19% identical).
Diseases named in the same sentence as UQCC1 in open-access papers:
UQCC1 is named in the same sentence as 12 diseases in open-access papers, as found by Europe PMC text mining. Sharing a sentence is not in itself a finding about the gene and the disease. The quoted sentences say what the papers report.
Obesity (2 papers, 2022 to 2024). Accumulation of substantial excess body fat. "Then, we use HCDC to analyze ARIC data and discovered that UQCC1-rs1570004 has a significant correlation with multiple phenotypes about obesity traits." (PMID 35391794, 2022). "Among these, UQCC1-rs1570004 is reported as a significant obesity signal for the first time, whose differential expression in subcutaneous fat, visceral fat, and muscle tissue is worthy of further functional studies." (PMID 35391794, 2022). "Thus, UQCC1-rs1570004, as a SNP that has not been reported to be associated with obesity-related phenotypes in other studies so far, is worthy of further functional experimental studies in the future to confirm its impressive value." (PMID 35391794, 2022). "Therefore, UQCC1-rs1570004, as an SNP that has not been reported to be associated to obesity-related phenotypes in the literature, is worthy of further functional experiments in the future to confirm its potential value." (PMID 35391794, 2022).
osteoarthritis (2 papers, 2023 to 2025). A noninflammatory degenerative joint disease occurring chiefly in older persons, characterized by degeneration of the articular cartilage, hypertrophy of bone at the margins and changes in the synovial membrane. "Polymorphisms in this gene have been linked to human height and osteoarthritis, and rs2378353 has been found to have a significant impact on the splicing of UQCC1 in muscle-skeletal tissue, as well as its expression in multiple tissues including fibroblasts, muscle-skeletal tissue, and skin." (PMID 37459304, 2023). "Genes associated with DDH and osteoarthritis include FRZB, CX3CR1, ASPN, DKK1, PDRG1, GDF5, UQCC1, and TGF-β1." (PMID 41019141, 2025).
developmental dysplasia of the hip (1 paper, 2023). A spectrum of hip abnormalities commonly presenting in infancy involving the relationship between the femoral head and the acetabulum and that includes subluxation or dislocation at rest or upon provocation. "An intronic variant of UQCC1 has been associated with developmental dysplasia of the hip in a Han Chinese population." (PMID 36662418, 2023).
ovarian carcinoma (1 paper, 2022). A malignant neoplasm originating from the surface ovarian epithelium. "Likewise, UQCC1, a protein involved in cytochrome b translation and/or stability, has been recently identified as a candidate ovarian cancer susceptibility gene." (PMID 35120576, 2022). "With regard to CTNNBL1, UQCC1 and CKB, all of them have been previously associated to ovarian cancer." (PMID 35120576, 2022). "The inverse correlation between UQCC1 and CDR2 expression in ovarian cancer (as highlighted by analysis of TCGA data), gives support to our results." (PMID 35120576, 2022). "Interestingly, it has been reported that UQCC1 physically interacts with CDR2, a target antigen of naturally occurring human tumor immunity, widely expressed in the majority of ovarian cancer." (PMID 35120576, 2022).
serous ovarian cancer (1 paper, 2022). "We therefore sought to determine whether any evidence exists for the relationship between UQCC1 and CDR2 in serous ovarian cancer." (PMID 35120576, 2022).
UQCC1 also shares sentences with these, for which no sentence is quoted: cancer (2 papers); tumor (2); colon tumor (1); male pattern baldness (1); metastatic tumors (1); papillary carcinoma (1); uveal melanoma (1).